S100A5 (S100 calcium binding protein A5)
Description:
Binds calcium, zinc and copper. One subunit can simultaneously bind 2 calcium ions or 2 copper ions plus 1 zinc ion. Calcium and copper ions compete for the same binding sites.
Synonyms: S100D
Tractability: No criterion of Open Targets' tractability assessment is met for any kind of drug.
Gene: Protein-coding gene on chromosome 1 (153,537,147 to 153,541,765, reverse strand). Ensembl gene ENSG00000196420.
Subcellular location (Human Protein Atlas): Nucleoplasm
Gene Ontology:
Molecular function: calcium ion binding; copper ion binding; protein binding; protein homodimerization activity; zinc ion binding; calcium-dependent protein binding; identical protein binding; transition metal ion binding
Cellular component: nucleus; neuronal cell body
Genetic constraint (gnomAD): Loss-of-function variants: 5 observed, 7.32 expected, observed/expected ratio (o/e) 0.68, 90% interval 0.36 to 1.42. That is too few expected variants to judge how well the gene tolerates losing a copy. Missense variants: 129 observed, 117.36 expected, observed/expected ratio (o/e) 1.1, 90% interval 0.95 to 1.27. Synonymous variants: 49 observed, 47.6 expected, observed/expected ratio (o/e) 1.03, 90% interval 0.82 to 1.31.
Homologues: Orthologues: chimpanzee S100A5 (99% identical), guinea pig S100A5 (96% identical), macaque S100A5 (96% identical), pig S100A5 (96% identical), mouse S100a5 (95% identical), rat S100a5 (95% identical), dog S100A5 (91% identical), rabbit S100A5 (91% identical), zebrafish s100t (50% identical), zebrafish s100s (48% identical), zebrafish s100a10a (35% identical), tropical clawed frog s100a11 (25% identical). Paralogues in human: S100A4 (51% identical), S100A2 (50% identical), S100A6 (49% identical), S100A1 (46% identical), S100B (43% identical), S100Z (43% identical), S100P (41% identical), S100A3 (39% identical), S100A13 (38% identical), S100A12 (36% identical), S100A10 (33% identical), S100A11 (33% identical), and 9 more.
Diseases named in the same sentence as S100A5 in open-access papers:
S100A5 is named in the same sentence as 17 diseases in open-access papers, as found by Europe PMC text mining. Sharing a sentence is not in itself a finding about the gene and the disease. The quoted sentences say what the papers report.
breast carcinoma (2 papers, 2017 to 2018). "S100A5, S100A6, S100A8 and S100A9 were correlated with prognosis in luminal A type breast cancer patients." (PMID 28051137, 2017).
colorectal cancer (2 papers, 2021 to 2023). A primary or metastatic malignant neoplasm that affects the colon or rectum. "S100A5 protein was also found in colorectal cancer cell lines, and S100A12 protein was found in EVs from brain cancer cells, colorectal cancer cells, melanoma cells, kidney cancer cells and more." (PMID 34721407, 2021).
ovarian carcinoma (2 papers, 2018 to 2021). A malignant neoplasm originating from the surface ovarian epithelium. "Whereas, some other S100 family members, including S100A3, S100A5, S100A7, S100A7A, S100A8, S100A16 and S100G are less reported in ovarian carcinoma." (PMID 30558666, 2018).
bladder cancer (1 paper, 2023). "In most carcinomas, S100A5 was expressed at significantly higher levels in tumor tissues than in normal tissues, including bladder cancer tissues." (PMID 37414584, 2023). "Targeting S100A5 converts cold tumors into hot tumors, thus enhancing the efficacy of immunotherapy in bladder cancer." (PMID 37414584, 2023). "MTT cell viability assays revealed that knockdown and overexpression of S100A5 significantly inhibited and promoted the proliferation of bladder cancer cells, respectively." (PMID 37414584, 2023). "The TissueFAXS cytometry panoramic tissue quantification assay was further applied to reveal the spatially exclusive role of S100A5+ bladder cancer cells and CD4+ and CD8+ T cells." (PMID 37414584, 2023). "S100A5 short hairpin RNA (sh‐S100A5) and S100A5‐cDNA (oe‐S100A5) and their negative controls (sh‐NC and oe‐vector respectively) were successfully transfected on human bladder cancer cell lines (T24 and 5637)." (PMID 37414584, 2023). "Systematic multi‐omics analysis identifies S100A5 as a novel immunosuppressive target for bladder cancer, which shapes a non‐inflamed tumor microenvironment in bladder cancer by inhibiting the secretion of pro‐inflammatory chemokines and the recruitment and cytotoxicity of CD8+ T cells." (PMID 37414584, 2023). "In addition, the colony formation assay confirmed that the knockdown and overexpression of S100A5 significantly inhibited and promoted the colony formation ability of bladder cancer cells, respectively." (PMID 37414584, 2023). "In addition, a wound healing assay revealed that S100A5 promoted bladder cancer cell invasion." (PMID 37414584, 2023). "We constructed a subcutaneous bladder cancer model by subcutaneously injecting S100A5 KD and negative control MB49 cells." (PMID 37414584, 2023). "S100A5 expression was the highest in epithelial cells, whereas no expression was observed in immune cells (such as CD4+ T, CD8+ T and NK cells) using another scRNA‐seq database containing two bladder cancer specimens (GSE130001)." (PMID 37414584, 2023).
bladder tumors (1 paper, 2023). "Third, to turn cold bladder tumors into hot ones, S100A5 small‐molecule inhibitors need to be developed in future research." (PMID 37414584, 2023).
colon adenocarcinoma (1 paper, 2023). "However, there was no significant negative correlation between S100A5 and TIICs in other carcinomas, such as lung adenocarcinoma (LUAD), sarcoma (SARC), breast invasive carcinoma (BRCA), and colon adenocarcinoma (COAD)." (PMID 37414584, 2023).
tumor (6 papers, 2018 to 2025). "The co‐expression of S100A5 on tumor cells and the exclusive role of S100A5 between CD4+ T and CD8+ T cells reached statistical significance in the whole TMA cohort." (PMID 37414584, 2023). "In summary, S100A5 shapes a non‐inflamed tumor microenvironment in BLCA by inhibiting the secretion of pro‐inflammatory chemokines and the recruitment and cytotoxicity of CD8+ T cells." (PMID 37414584, 2023). "Using sc‐RNA‐seq data, we found that S100A5 was specifically expressed in tumor cells and barely expressed in other cells, both in the TME and blood." (PMID 37414584, 2023). "For further spatial analysis, we quantified the number of CD4+ and CD8+ T cells within the distance gradients of S100A5+CK19+ tumor cells (0‐25 μm, 25–50 μm, 50–100 μm, and 100–150 μm)." (PMID 37414584, 2023). "Clinically, there was a spatially exclusive relationship between S100A5+ tumor cells and CD8+ T cells in tissue microarrays." (PMID 37414584, 2023). "S100A5 shapes a non‐inflamed tumor microenvironment in BLCA by inhibiting the secretion of pro‐inflammatory chemokines and the recruitment and cytotoxicity of CD8+ T cells." (PMID 37414584, 2023). "Second, although S100A5 could mediate tumor immune evasion by regulating chemokine secretion and CD8+ T cell cytotoxicity, further detailed mechanisms are required." (PMID 37414584, 2023). "S100A5 knockdown or anti‐PD‐1 treatment alone significantly suppressed the tumor burden in vivo." (PMID 37414584, 2023). "In addition, S100A5 acted as an oncogene, thereby promoting tumor proliferation and invasion." (PMID 37414584, 2023). "However, S100A5 knockdown plus anti‐PD‐1 treatment showed the highest efficacy in inhibiting tumor burden, indicating that S100A5 downregulation could enhance the efficacy of anti‐PD‐1 treatment." (PMID 37414584, 2023). "In addition, we found that S100A5 was significantly higher in the tumor tissues in our TMA." (PMID 37414584, 2023). "In a large immunotherapy cohort of BLCA (IMvigor210), we found that S100A5 expression was highest in the desert immune phenotype, TC0 (lowest PD‐L1 expression on tumor cells), and IC0 (lowest PD‐L1 expression on immune cells)." (PMID 37414584, 2023). "In non‐inflamed tumors, the wide expression of S100A5 in tumor cells inhibited the infiltration of CD4+ and CD8+ T cells into the tumor region (non‐inflamed)." (PMID 37414584, 2023). "Moreover, the flow‐like cytometry plots show that S100A5 was positively expressed mainly in CK19+ tumor cells (58.84%), but almost not in CD4+ T cells (2.45%) or CD8+ T cells (4.15%)." (PMID 37414584, 2023). "As S100A5, S100A7, S100A7A, S100Z, TCHHL1, and S100G are ubiquitously expressed at low levels in both tumor and paratumor samples, they were not included in the following analyses." (PMID 37133437, 2023). "In contrast, none of S100A5 expression tumors exhibited an inflamed phenotype, with numerous CD4+ and CD8+ T cells infiltrating the tumor regions (inflamed)." (PMID 37414584, 2023).
cancer (3 papers, 2020 to 2024). A tumor composed of atypical neoplastic, often pleomorphic cells that invade other tissues. "Pan‐cancer analyses revealed that the immunosuppressive role of S100A5 in the TME was most evident in BLCA." (PMID 37414584, 2023). "We then performed pan‐cancer analyses of S100A5 in 33 types of carcinomas." (PMID 37414584, 2023). "Furthermore, S100A5 attenuated effector T cell killing of cancer cells by inhibiting CD8+ T cell proliferation and cytotoxicity." (PMID 37414584, 2023). "Interestingly, when cancer cell lines were not co‐cultured with T lymphocytes, knockdown or overexpression of S100A5 alone inhibited or promoted cancer cell proliferation, respectively." (PMID 37414584, 2023). "In summary, we found that S100A5 could act as an oncogene and inhibit cancer cell death by inhibiting CD8+ T cell proliferation and cytotoxicity." (PMID 37414584, 2023). "Furthermore, pan‐cancer analyses through 33 types of carcinomas revealed that the immunosuppressive role of S100A5 in the TME was most obvious in BLCA." (PMID 37414584, 2023). "Some studies have found that S100A5 weakens the killing of BLCA cells by effector T cells by inhibiting CD8+ T cell proliferation and cytotoxicity, thereby exerting anti-cancer immunity and further reducing the effectiveness of anti-PD-L1/PD-1 immunotherapy." (PMID 39659999, 2024). "In summary, we found that only S100A5 shaped a non‐inflamed TME specifically in BLCA, by correlating multiple S100 proteins with multiple cancer types." (PMID 37414584, 2023). "Next, we calculated the pan‐cancer T cell‐inflamed score (TIS) and found that the S100A5 was significantly negatively correlated (R = −0.29, p < 0.001)." (PMID 37414584, 2023). "Therefore, we first analyzed the expression patterns of these proteins in the TCGA‐BLCA and Xiangya BLCA cohorts and found that S100A5, S100A7, S100A11, S100A14‐16, and S100B were significantly higher in carcinoma tissues than normal tissues in both cohorts." (PMID 37414584, 2023). "Importantly, the negative correlation between S100A5, the cancer‐immune cycle, and TIICs was validated in the Xiangya cohort, indicating a robust predictive value of S100A5 for TIICs in BLCA." (PMID 37414584, 2023). "Based on the Oncomine database, there are no obvious distinctions in S100A1, S100A4, S100A5, S100A6, and S100A13 expressions between cancer tissues and normal colon mucosa, and S100A7, S100A12, and S100Z are slightly overexpressed in CRC tissues." (PMID 33294444, 2020).
infection (1 paper, 2022). The state of being infected such as from the introduction of a foreign agent such as serum, vaccine, antigenic substance or organism. "S100a5 is expressed primarily in neuronal bodies, and Tchh is expressed in the tongue and hair; neither appears to be involved in the response to infection." (PMID 35880881, 2022).
S100A5 also shares sentences with these, for which no sentence is quoted: alcohol abuse (1 paper); astrocytoma (1); endometrial carcinoma (1); glioma (1); lung adenocarcinoma (1); meningioma (1); sarcoma (1); serous ovarian cancers (1).